PDIK1L (PDLIM1 interacting kinase 1 like)
Synonyms: CLIK1L; STK35L2
Tractability: Small molecule: it belongs to a druggable protein family. PROTAC: it is named in the literature on targeted protein degradation; ubiquitination databases record sites on it.
Gene: Protein-coding gene on chromosome 1 (26,111,157 to 26,125,555, forward strand). Ensembl gene ENSG00000175087.
Subcellular location: Nucleus
Subcellular location (Human Protein Atlas): Nucleoplasm
Gene Ontology:
Molecular function: protein binding; ATP binding; protein kinase activity; protein serine kinase activity; protein serine/threonine kinase activity
Biological process: negative regulation of G2/M transition of mitotic cell cycle; negative regulation of G2/MI transition of meiotic cell cycle
Cellular component: nucleoplasm; cytoplasm; nucleus
Genetic constraint (gnomAD): Loss-of-function variants: 9 observed, 28.37 expected, observed/expected ratio (o/e) 0.32, 90% interval 0.19 to 0.55. The upper end of that interval is the gene's LOEUF score, 0.55, which puts it in group 2 of 6, group 1 being the genes least tolerant of losing a copy. Missense variants: 216 observed, 436.09 expected, observed/expected ratio (o/e) 0.5, 90% interval 0.44 to 0.55. Synonymous variants: 130 observed, 149.52 expected, observed/expected ratio (o/e) 0.87, 90% interval 0.75 to 1.01.
Homologues: Orthologues: chimpanzee PDIK1L (100% identical), macaque PDIK1L (100% identical), pig PDIK1L (99% identical), rabbit PDIK1L (99% identical), rat Pdik1l (99% identical), dog PDIK1L (99% identical), guinea pig PDIK1L (99% identical), mouse Pdik1l (99% identical), zebrafish pdik1l (83% identical), tropical clawed frog pdik1l (82% identical), Drosophila melanogaster Wee1 (20% identical). Paralogues in human: STK35 (68% identical), EIF2AK3 (22% identical), WEE1 (21% identical), EIF2AK4 (19% identical), PKMYT1 (19% identical), EIF2AK2 (19% identical), WEE2 (19% identical), EIF2AK1 (18% identical).
Diseases named in the same sentence as PDIK1L in open-access papers:
PDIK1L is named in the same sentence as 25 diseases in open-access papers, as found by Europe PMC text mining. Sharing a sentence is not in itself a finding about the gene and the disease. The quoted sentences say what the papers report.
acute myeloid leukemia (1 paper, 2024). Acute myeloid leukemia (AML) is a group of neoplasms arising from precursor cells committed to the myeloid cell-line differentiation. "In acute myeloid leukemia (AML), CTDSPL2 dephosphorylates the kinases STK35 and PDIK1L, supporting the proliferation of AML cancer cells and affecting the expression of genes involved in amino acid biosynthesis and transport." (PMID 39209829, 2024).
prostate carcinoma (1 paper, 2025). A carcinoma that arises from epithelial cells of the prostate gland. "In conclusion, our findings bridge metabolic diversity with genomic instability in prostate cancer, positioning PDIK1L as a pivotal node for therapeutic intervention." (PMID 41262299, 2025). "Our data show that PDIK1L not only promotes prostate cancer proliferation but also enhances glycogen metabolism and improve sensitivity to PARP inhibitors." (PMID 41262299, 2025). "Collectively, these results confirm that PDIK1L drives prostate cancer proliferation and modulates PARP inhibitor efficacy, positioning it as both a therapeutic target and predictive biomarker for combinatorial therapies." (PMID 41262299, 2025). "Functional studies utilized prostate cancer cell lines with genetic modulation of PDIK1L." (PMID 41262299, 2025). "Mechanistically, PDIK1L may stabilize oncogenic signaling by modulating DNA repair or metabolic adaptations, akin to OTUD6A, a deubiquitinase recently shown to stabilize c-Myc and promote metabolic remodeling in prostate cancer." (PMID 41262299, 2025).
tumor (8 papers, 2007 to 2025). "PDIK1L emerges as a dual-functional biomarker driving tumor progression and modulating treatment efficacy, offering a novel target for precision therapeutic strategies." (PMID 41262299, 2025). "Integrative multi-omics and random survival forest analysis prioritized PDIK1L as a C2-specific biomarker, where its overexpression accelerated tumor proliferation and rewired metabolic programs to confer resistance to PARP inhibitors." (PMID 41262299, 2025). "Upregulated genes were associated with the meiotic cell cycle (PDIK1L) and tumor proliferation (BACH1 and PDIK1L)." (PMID 41333405, 2025). "The prioritization of PDIK1L as a C2-specific biomarker underscores its dual role in tumor proliferation and therapy resistance." (PMID 41262299, 2025).
cancer (7 papers, 2005 to 2025). A tumor composed of atypical neoplastic, often pleomorphic cells that invade other tissues. "Mechanistically, PDIK1L’s interaction with nucleotide biosynthesis pathways could deplete dNTP pools, exacerbating replication stress and genomic instability in C2 tumors—a phenomenon observed in BRCA1-deficient cancers treated with PARPi." (PMID 41262299, 2025).
PDIK1L also shares sentences with these, for which no sentence is quoted: breast carcinoma (2 papers); advanced sleep phase syndrome (1); Alzheimer disease (1); cholangiocarcinoma (1); cystic fibrosis (1); Familial advanced sleep-phase syndrome (1); glioma (1); infection (1); Insulin resistance (1); lung adenocarcinoma (1); migraine (1); Monge’s disease (1); mood disorder (1); multiple myeloma (1); neuroblastoma (1); Raine Syndrome (1); RASopathy (1); Salmonella Infections (1); schizophrenia (1); triple-negative breast carcinoma (1); urothelial carcinoma (1).